MYLK3 (myosin light chain kinase 3)
Description:
Kinase that phosphorylates MYL2 in vitro (By similarity). Has been proposed to be calmodulin-dependent, although MYL2 phosphorylation has also been observed in the presence or absence of calmodulin (By similarity). Promotes sarcomere formation in cardiomyocytes and increases cardiomyocyte contractility (By similarity).
Synonyms: MLCK; caMLCK; MLCK2
Tractability: Small molecule: a high-quality ligand is known; it belongs to a druggable protein family. PROTAC: ubiquitination databases record sites on it; a small molecule that binds it is known.
Target class: Kinase; CAMK protein kinase MLCK family; CAMK protein kinase group; Enzyme; Protein Kinase
Gene: Protein-coding gene on chromosome 16 (46,702,282 to 46,790,407, reverse strand). Ensembl gene ENSG00000140795.
Subcellular location: Cytoplasm
Subcellular location (Human Protein Atlas): Nucleoplasm; Cytosol; Vesicles
Gene Ontology:
Molecular function: protein binding; calcium/calmodulin-dependent protein kinase activity; myosin light chain kinase activity; ATP binding; protein kinase activity
Biological process: cellular response to interleukin-1; positive regulation of membrane permeability; positive regulation of tight junction disassembly; cardiac myofibril assembly; positive regulation of sarcomere organization; sarcomere organization; sarcomerogenesis; signal transduction
Cellular component: actin cytoskeleton; cytoplasm; cytosol
Genetic constraint (gnomAD): Loss-of-function variants: 54 observed, 71.32 expected, observed/expected ratio (o/e) 0.76, 90% interval 0.61 to 0.95. The upper end of that interval is the gene's LOEUF score, 0.95, which puts it in group 4 of 6, group 1 being the genes least tolerant of losing a copy. Missense variants: 949 observed, 1,029.1 expected, observed/expected ratio (o/e) 0.92, 90% interval 0.87 to 0.97. Synonymous variants: 406 observed, 419.26 expected, observed/expected ratio (o/e) 0.97, 90% interval 0.89 to 1.05.
Gene-disease validity (ClinGen):
ClinGen rates the evidence that MYLK3 causes each of these diseases.
dilated cardiomyopathy (autosomal dominant): Moderate. Cardiomyopathy which is characterized by dilation and contractile dysfunction of the left and right ventricles.
Homologues: Orthologues: chimpanzee MYLK3 (99% identical), rabbit MYLK3 (76% identical), pig MYLK3 (74% identical), guinea pig MYLK3 (72% identical), mouse Mylk3 (69% identical), rat Mylk3 (67% identical), dog MYLK3 (66% identical), tropical clawed frog mylk3 (44% identical), zebrafish mylk3 (34% identical). Paralogues in human: MYLK2 (31% identical), MYLK4 (27% identical), DCLK1 (19% identical), DCLK2 (19% identical), DCLK3 (15% identical), CAMKV (14% identical), CAMK2D (13% identical), CAMK1 (13% identical), CAMK1D (13% identical), CAMK2G (13% identical), CAMK1G (13% identical), CAMK2A (13% identical), and 10 more.
Diseases named in the same sentence as MYLK3 in open-access papers:
MYLK3 is named in the same sentence as 22 diseases in open-access papers, as found by Europe PMC text mining. Sharing a sentence is not in itself a finding about the gene and the disease. The quoted sentences say what the papers report.
heart failure (5 papers, 2016 to 2022). Inability of the heart to pump blood at an adequate rate to meet tissue metabolic requirements. "Conditional adult-onset Mylk3 knockout mice have drastically reduced MYL2 phosphorylation which precedes heart failure, whereas germ line ablation causes mice to develop DCM in adulthood, and perinatal ablation produces an intermediate phenotype." (PMID 32213617, 2020). "The clinical phenotypes of DCM patients were consistent with MYLK3 loss-of-function mouse and zebrafish models in which cardiac enlargement and heart failure are observed." (PMID 29235529, 2017). "When, in genetically modified mice, cMLCK encoded by Mylk3 gene, was ablated either from the germline or inducibly in adulthood, both populations of cMLCK-deficient mice exhibited heart failure." (PMID 27833563, 2016). "Heterozygous Mylk3 knockout mice demonstrate mild heart failure with markedly reduced expression of cMLCK proteins discordant with mRNA level." (PMID 31244672, 2019). "Nkx2-5 regulates multiple downstream targets including cMLCK, and perinatal Nkx2-5-KO mice demonstrate more profound heart failure compared to perinatal Mylk3-KO mice, with a 1.44 fold increase of HW/BW ratio at P12." (PMID 27833563, 2016). "We previously generated and examined homozygous Mylk3 knockout mice that lead to heart failure." (PMID 31244672, 2019). "Although these results suggest that the reduced cMLCK expression in the patient with MYLK3 mutation is not secondary to heart failure, but due to a pathological consequence of mutated MYLK3, we need more heart samples to reach conclusion." (PMID 29235529, 2017). "Based on the profound heart failure seen in adult-inducible Mylk3-KO mice, nonetheless, we speculate that their cardiac function is unlikely to improve in later life." (PMID 27833563, 2016). "Because of this, we presume that the reduction in body weight observed in the perinatal Mylk3-KO mice is due to heart failure, but we cannot rule out the possibility that cMLCK may directly regulate body weight by unknown mechanisms." (PMID 27833563, 2016). "Given the lethality of conditional adult MYLK3 knockouts, it has been suggested that the lack of MYLK3 in germ line knockouts during development allows the heart to adapt, whereas this ability is lost when the knockout is induced in adulthood, as these mice develop heart failure and die." (PMID 32213617, 2020).
cardiomyopathy (4 papers, 2017 to 2025). A disease of the heart muscle or myocardium proper. "One exception from this were two DCM patients with LP variants in MYLK3, which is not an established cardiomyopathy gene but has emerging evidence of pathogenicity." (PMID 39910139, 2025). "Although the importance of cMLCK for proper cardiac function is strongly suggested by animal cardiomyopathy models in vivo and experimental data in vitro, no MYLK3 mutation has been identified as a pathogenic factor of human cardiomyopathy." (PMID 29235529, 2017). "To examine whether other MYLK3 variants cause DCM, we first conducted targeted sequencing in our 52-patient unrelated DCM cohort and identified 15 patients (8 familial and 7 sporadic) with uncharacterized genetic etiology in known cardiomyopathy-related genes." (PMID 29235529, 2017). "Genes associated with ER stress (e.g., ATF4, NUPR1, DDIT3, TRIB3, CHAC1, SESN2, HERPUD1) were upregulated and genes related to cardiomyopathy and sarcomeric structure (e.g., MYH7, SYNPO2L, LDB3, ACTN2, MYLK3) were downregulated by afatinib, sorafenib, or high-dose ponatinib." (PMID 37069550, 2023). "Genetic differences between C57BL/6 substrains lead to different cardiovascular traits; a null mutation in Mylk3 likely causes cardiomyopathy in C57BL/6N mice, whereas C57BL/6J Nnt-null mice do not develop cardiomyopathy." (PMID 32213617, 2020). "We then conducted MYLK3 gene screening of 15 DCM patients (7 familial and 8 sporadic) who were negative for mutation screening of the previously-reported cardiomyopathy-causing genes, and identified another case with a MYLK3 frameshift mutation (c.1879_1885del; p.L627fs*41)." (PMID 29235529, 2017).
dilated cardiomyopathy (3 papers, 2021 to 2025). "These genetic differences, including over 50 coding and structural variants can influence cardiovascular phenotypes, with 6N mice displaying age-related dilated cardiomyopathy linked primarily to Mylk3 deficiency." (PMID 41432818, 2025). "WES revealed that MYLK3 mutations are associated with dilated cardiomyopathy in humans." (PMID 37760246, 2023). "Similarly, a loss of function mutation in myosin light chain kinase 3 (Mylk3) has been described in C57BL6/N, but not C57BL6/J, which is associated with mild dilated cardiomyopathy at 12 months of age." (PMID 34054587, 2021).
ovarian carcinoma (3 papers, 2017 to 2022). A malignant neoplasm originating from the surface ovarian epithelium. "It was revealed that patients with MYLK3 methylation showed prolonged overall survival in ovarian cancer treated with surgery." (PMID 35509066, 2022).
familial dilated cardiomyopathy (2 papers, 2017 to 2019). A a genetic form of heart disease that occurs when heart (cardiac) muscle becomes thin and weakened in at least one chamber of the heart, causing the open area of the chamber to become enlarged (dilated). "Backgrounds: Recent studies identified heterozygous variants in MYLK3 gene that encodes cardiac myosin light chain kinase (cMLCK) are related to familial dilated cardiomyopathy (DCM) for the first time." (PMID 31244672, 2019). "In addition, recent studies showed that heterozygous human mutations in MYLK3 gene could be related to familial dilated cardiomyopathy (DCM)." (PMID 31244672, 2019).
Arrhythmia (1 paper, 2017). Any cardiac rhythm other than the normal sinus rhythm. "None of the MYLK3-related DCM patients developed a life-threatening arrhythmia or required heart transplantation during follow-up." (PMID 29235529, 2017).
basal cell carcinoma (1 paper, 2022). A carcinoma involving the basal cells. "The expression of CACNA1S, ATP2A1, RYR1, and MYLK3 was upregulated in MAC compared with normal sweat glands and syringoma tumor cells and was generally negative in trichoepithelioma and infundibulocystic type basal cell carcinoma." (PMID 35509066, 2022). "We demonstrated that the CACNA1S, MYLK3, RYR1, and ATP2A1 proteins were more highly expressed in MAC tumor cells than in normal sweat glands and syringoma, while were generally negative in tumor cells of trichoepithelioma and basal cell carcinoma, infundibulocystic type." (PMID 35509066, 2022).
tumor (4 papers, 2017 to 2025). "The four candidate genes (CACNA1S, ATP2A1, RYR1, and MYLK3) of Ca2+ signaling have special functions in tumor progression." (PMID 35509066, 2022). "In the BRCA tumor sample, a region of the anti-sense strand of gene MYLK3 is inserted after the third exon of the ZFHX3 gene." (PMID 29650026, 2018). "The MYLK3 biomarker could potentially be measured from tumour biopsy samples or from cell-free circulating tumour DNA." (PMID 28350786, 2017). "In the meantime, differential methylation at the cg13247990 MYLK3 locus appears to have significant potential as a surgical biomarker, which may enable stratification of surgical care according to the biology of patients’ tumours." (PMID 28350786, 2017). "Although the genes in (PRKAA2, GNG7, MYL3, NOS1, ADCY1, PLCB1, MYLK3, and MYLK4) the apelin/APJ signaling axis are found to be downregulated and might not be considered responsible in cdRCC progression, downregulation of GNG7 tells a different story due to its tumor‐suppressive activity." (PMID 40304310, 2025).
cancer (3 papers, 2022 to 2023). A tumor composed of atypical neoplastic, often pleomorphic cells that invade other tissues. "MYLK3 also is a member of the MAPK signaling pathway, another cancer-related signaling pathway." (PMID 35509066, 2022).
myopathy (1 paper, 2025). A disease of the muscle in which the muscle fibers do not function properly. "The three patients that would not have been detected using this approach were: one patient with DCM without any documentation of myopathy with a LP variant in DMD, and two patients with DCM and LP variants in MYLK3." (PMID 39910139, 2025).
MYLK3 also shares sentences with these, for which no sentence is quoted: endothelial dysfunction (2 papers); amebiasis (1); breast carcinoma (1); gastric carcinoma (1); Hypertension (1); infection (1); inflammation (1); influenza (1); prostate carcinoma (1); Sepsis (1); syringoma (1); trichoepithelioma (1).